TEX47 (testis expressed 47)
Synonyms: C7orf62; MGC26647; DYBLUF
Tractability: No criterion of Open Targets' tractability assessment is met for any kind of drug.
Gene: Protein-coding gene on chromosome 7 (88,794,106 to 88,795,737, reverse strand). Ensembl gene ENSG00000164645.
Gene Ontology:
Molecular function: protein binding
Genetic constraint (gnomAD): Loss-of-function variants: 18 observed, 18.95 expected, observed/expected ratio (o/e) 0.95, 90% interval 0.66 to 1.41. The upper end of that interval is the gene's LOEUF score, 1.41, which puts it in group 5 of 6, group 1 being the genes least tolerant of losing a copy. Missense variants: 303 observed, 316.66 expected, observed/expected ratio (o/e) 0.96, 90% interval 0.87 to 1.05. Synonymous variants: 98 observed, 115.01 expected, observed/expected ratio (o/e) 0.85, 90% interval 0.72 to 1.01.
Homologues: Orthologues: chimpanzee TEX47 (98% identical), macaque TEX47 (94% identical), pig TEX47 (78% identical), dog TEX47 (74% identical), rabbit TEX47 (72% identical), mouse Tex47 (70% identical), rat Tex47 (70% identical), tropical clawed frog tex47 (31% identical), zebrafish tex47 (27% identical).